FABP4 (fatty acid binding protein 4)
Diseases named in the same sentence as FABP4 in open-access papers (continued):
Sharing a sentence is not in itself a finding about the gene and the disease.
cancer (continued). "The adipocytes in turn induce the expression of fatty acid-binding protein 4 (FABP4), a fatty acid transporter in the cancer cells, which facilitates efficient cancer cell uptake of free fatty acids (FFAs) released by the adipocytes." (PMID 32780245, 2020). "FABP4 and FABP5 are involved in tumorigenesis in different cancer types, including colorectal, prostate, oral, glioma, ovarian, and breast cancer." (PMID 33050166, 2020). "Except for FABP5, mRNA levels of FABP12, FABP4, FABP9 and FABP8 were upregulated in cancers with higher Gleason scores." (PMID 33352874, 2020). "Of these five FABPs, FABP4 and FABP5 have been the most intensively studied in terms of progression of various cancers, including PCa." (PMID 33352874, 2020). "Microarray analysis with Oncomine data also revealed increased expression levels of FABP4 and CD36 in metastatic prostate cancer compared to those of the primary cancer." (PMID 31334678, 2019). "FABP4 silencing led to a significant reduction in both migration and invasion of HeyA8 MDR cancer cells (p < 0.01)." (PMID 30050129, 2018). "Previous study indicated that FABP4 regulated the VEGF and promoted the proliferation of HUVEC, and it also reported in various cancers." (PMID 29733540, 2018). "In summary, our current study, for the first time, demonstrates the roles of FABP4 in adipocyte-CCA interactions, as well as in the energy extraction of CCA cells from cancer related adipocytes." (PMID 29237483, 2017). "The potential roles of FABP‐4 and the mechanisms by which FABP‐4 may be involved in cancer progression were studied in several experiments." (PMID 40857027, 2026). "FABP4-mediated lipid metabolism facilitated TNBC progression and cancer stem cell characteristics." (PMID 40604951, 2025). "Under stress conditions like hypoxia, where de novo FA synthesis is compromised, cancer cells compensate by absorbing external lipids, orchestrated by the master regulator HIF‐1α and lipid‐binding proteins like fatty acid‐binding protein 4 (FABP4)." (PMID 39969135, 2025). "Both FABP4 and CD36 have been suggested as emerging therapeutic targets for cancer." (PMID 38748262, 2024). "FABP4 is important in FAO and cancer cell survival in both solid and hematologic cancers." (PMID 37065866, 2023). "Mechanistically, SCD1 catalyzes the fatty acid desaturation to produce monounsaturated fatty acids (MUFA), leading to ferroptosis inhibition in cancer cells, while FABP4 in the TME sustains lipid droplet (LD) formation and promotes cancer cell survival under hypoxia-induced ferroptosis." (PMID 37048123, 2023). "Next to CAAs, FABP4 expression is found on TAMs and a variety of cancer cells; thus, radioligand uptake is not CAA specific." (PMID 35788730, 2022). "Moreover, FABP4 and FABP5—known to be regularly expressed during adipocyte differentiation—have been found at high levels in cancers of the prostate, breast, and ovaries, where they promote malignant progression and metastasis and worsen prognosis." (PMID 36497485, 2022). "In addition to FABP4, CD36 appears as an interesting metabolic target to limit metastatic progression in cancer." (PMID 35945203, 2022). "Conform our scRNA-seq findings, microvascular ECs exclusively expressing FABP4 or ID2 could be identified in human breast (cancer) tissue." (PMID 36127427, 2022). "Various studies have reported the potential for CD36 and FABP4 to be targeted for therapy in different cancers, indicating that targeting either CD36, FABP4 or both may provide therapeutic opportunities." (PMID 34561446, 2021). "Specifically, LPL has mainly localized the periphery of cancer cells; CPT1 is mainly localized in the cytoplasm of cancer cells; FABP4 showed a certain degree of fuzzy staining in the cancer cells, which may be caused by its secretory status." (PMID 34803493, 2021).
cancer (continued). "Nuclear translocation of FABP4 and FABP5 proteins mediated by lipid ligands, including EETs, can activate transcription factors (TFs) to initiate proliferative or cell death signaling in several cancer models." (PMID 31941087, 2020). "In addition, five genes involved in the 47-mRNA metastasis-related model, including FABP4, GUCY2C, MEIS2, POU1F1, and SLC25A11 have been reported to be related to the metastasis of other human cancers." (PMID 33159021, 2020). "Therefore, we studied whether MMP9, MMP12, FABP4, and CD36 genes are correlated with poor prognosis in various cancers." (PMID 37978381, 2023). "Since abnormal lipid metabolism is essential for the activity of cancer stem cell maintenance 26, 27, we assumed that the activation of the LPL/FABP4/CPT1 metabolic axis may be an important promoter to facilitate the progression of NASH to HCC through collaboration with oncogenic signals." (PMID 34803493, 2021). "However, the upregulated genes of macrophages with FABP4 overexpression was significantly enriched in the ECM‐receptor interaction pathway, which plays a role in cell–substrate junction and has been reported closely related to cancer metastases." (PMID 33931964, 2021). "Once EOC cells lodge onto the omentum, proximity to adipocytes results in upregulation of fatty-acid-binding protein 4 (FABP4) and a fatty-acid receptor CD36, followed by transfer of lipids from adipocytes to EOC cells, and induction of lipolysis in adipocytes and β-oxidation in cancer cells." (PMID 30445726, 2018). "Numerous studies have proved that FABP4, COL4A1, and RGS4 were related to various types of cancer progression; however, we searched GIST on PubMed with no reports on our screened differential genes and GIST." (PMID 35646090, 2022). "We further confirmed that ABCA8 and FABP4 expression were significantly decreased in STAD tissues, regardless of clinical characteristics, such as cancer stage, grade, and nodal metastasis status of STAD." (PMID 32685482, 2020). "Due to variations between datasets, FABP4 expression did not predict patient disease-free survival in the TCGA Firehose Legacy dataset, while U2AF2, RUVBL1, XPO1, and POSTN did not predict disease-free survival in the BS Taylor, Cancer Cell, 2010 dataset." (PMID 39402324, 2024).
cardiovascular disease (90 papers, 2011 to 2025). "Fabp4 (fatty acid-binding protein 4) is a fatty acid transporter whose elevated levels have been associated with multiple age-related metabolic and cardiovascular disorders." (PMID 41509418, 2025). "Further research on FABP4 genetics and its putative causal role in cardiovascular disease is needed, particularly in aging subgroups." (PMID 38698167, 2024). "More recently, this variant was shown to decrease FABP4 expression in epicardial adipose tissue and associates with risk for cardiovascular disease in type 1 diabetes patients." (PMID 38698167, 2024). "FABP4 is established as a reliable predictive biomarker for cardiovascular disease in specific at-risk groups." (PMID 38698167, 2024). "The association of circulating FABP4 levels with cardiovascular disease has been studied extensively in observational studies." (PMID 38698167, 2024). "Accumulating evidence for the pathogenic role of FABP4 in cardiovascular events suggests that FABP4 is a potential new target for preventing cardiovascular diseases." (PMID 36611783, 2023). "Elevated levels of FABP4 in the blood are associated with metabolic disorders and cardiovascular diseases." (PMID 35563118, 2022). "There is available data to suggest that higher levels of FABP4 are also associated with elevated cardiovascular diseases mortality among men with T2DM." (PMID 30857223, 2019). "Elevated circulating hsCRP and pro-inflammatory adipocytokines like FABP4, leptin and lipocalin-2 increase the risk for cardiovascular disease by not only endocrine but also paracrine mechanisms." (PMID 30395653, 2018). "A genetic variant at the FABP4 locus associated with decreased FABP4 expression in adipose tissue has been reported to reduce the risk of cardiovascular disease in a population study." (PMID 25142635, 2014). "Thus, the levels of FABP4 in the bloodstream are positively associated to many symptoms of metabolic syndrome and cardiovascular disease." (PMID 39599599, 2024). "Data from animal studies also support the pathogenic role of FABP4 in cardiovascular disease." (PMID 24312381, 2013). "Subjects with a genetic variation of the FABP4 locus (T-87C) leading to decreased FABP4 expression in adipose tissue showed lower levels of triglycerides as well as a significantly reduced risk for cardiovascular disease." (PMID 22102888, 2011). "We analysed other biomarkers that, in recent years, have been related to cardiovascular disease, such as suPAR, FABP4, and MM biomarkers (P, PTH, vitamin D, FGF-23, klotho)." (PMID 39940753, 2025). "The potential of FABP4 as a therapeutic target for metabolic and cardiovascular disease has already been widely discussed." (PMID 40002815, 2025). "Furthermore, it has been shown that FABP4 is an inducible factor for angiogenesis and vascular smooth muscle cell proliferation and migration, and FABP4 has therefore been established as a reliable predictive biomarker for cardiovascular disease in specific at-risk groups." (PMID 39062961, 2024). "Lipolysis, caused by an elevated adrenergic input, has been suggested to contribute to elevated serum FABP4 levels in patients with cardiovascular diseases." (PMID 39725654, 2024). "Circulating fatty acid-binding protein 4 (FABP4) influences cardiovascular disease and glucose metabolism." (PMID 39707536, 2024). "Previous studies using animal models showed that FABP4 contributes to the development of metabolic disorders and cardiovascular disease in communication with metabolic and inflammatory pathways in adipocytes and macrophages." (PMID 33597568, 2021). "Circulating fatty acid binding protein 4 (FABP4), secreted from adipocytes, is a potential biomarker for metabolic and cardiovascular diseases." (PMID 30401801, 2018). "In cardiovascular disease patients, the pericardial cavity is a distinct adipocytokine microenvironment in which especially FABP4 is mainly derived from the heart." (PMID 30395653, 2018).
cardiovascular disease (continued). "Here, we discuss one specific protein, which is equally important for meat quality, feed efficiency, and milk content variability in livestock as it is for lipid metabolism in health and cardiovascular disease (CVD) in humans: fatty acid-binding protein 4 (FABP4)." (PMID 38698167, 2024). "The role of FABP4 in metabolic and cardiovascular diseases has been extensively explored." (PMID 35052876, 2022). "The association among ADMA, FABP4 and AIP in a cross-sectional study of 340 healthy women may also explain why AIP could be a biomarker for cardiovascular disease." (PMID 36429582, 2022). "Serum FABP4, age, and albumin remained significantly associated with the AAC score in PD patients after adjustment for the history of cardiovascular disease, systolic BP, diastolic BP, residual kidney Kt/V, serum corrected calcium, us-CRP, TG, HDL-C, skeletal muscle mass, and body fat mass." (PMID 34789046, 2021). "Univariate linear regression analyses demonstrated that serum FABP4, age, the history of cardiovascular disease, serum corrected calcium, corrected calcium >2.54 mmol/L, us-CRP, TG, body fat mass, body fat percentage, and lean body mass were positively associated with the AAC score (p < 0.1)." (PMID 34789046, 2021). "FABP4 is an adipokine widely studied in metabolic and cardiovascular diseases." (PMID 31931795, 2020). "Despite the strong evidence showing the effect of plasma FABP4 concentration on cardiovascular diseases, the relationship between plasma FABP4 level and electrocardiographic parameters are unknown, especially its arrhythmogenic effect on the QTc interval." (PMID 31234795, 2019). "A community-based cohort study reported that the cardiovascular diseases could be predicted with the circulating FABP4 level." (PMID 30969942, 2019). "FABP4 concentration may be not only a marker of metabolic disorders but also a predictor of cardiovascular mortality in a general population as well as in patients with metabolic and cardiovascular diseases." (PMID 33597568, 2021). "We recently determined the levels of fatty acid-binding protein 4 (FABP4), leptin, and adiponectin in not only the circulation but also the pericardial fluid from a small number of cardiovascular disease patients." (PMID 30395653, 2018). "In this sense, plasmatic FABP4 levels were not demonstrated to be a good indicator of MRA effects on epicardial fat from patients with cardiovascular disease." (PMID 35455943, 2022). "Reduction of FABP4 level as a possible class and pleiotropic effect of DPP-4 inhibitors might be beneficial for patients with metabolic and cardiovascular diseases." (PMID 32539832, 2020). "We therefore speculate that the elevated levels of FABP4 in COPD patients, especially in females, may link COPD with metabolic and cardiovascular disorders." (PMID 26823558, 2016).
metabolic disease (90 papers, 2011 to 2026). A congenital disorder (due to inherited enzyme abnormality) or acquired (due to failure of a metabolically important organ) disorder resulting from an abnormal metabolic process. "Fatty acid-binding protein 4 (FABP4), an adipokine associated with metabolic disorders, is recognized as a pivotal modulator of inflammatory responses; however, its role in ICH-induced SBI remains undefined." (PMID 41204337, 2025). "Greater basal FABP4 concentration in circulation is associated with the pathogenesis of metabolic disorders." (PMID 40285451, 2025). "FABP4 is involved in lipid transport and metabolism, and its elevated expression is often associated with adipogenesis and metabolic disorders." (PMID 40508039, 2025). "Numerous studies have reported that FABP4 is associated with the development of metabolic disorders and cardiovascular diseases in conjunction with metabolic and inflammatory pathways." (PMID 38731797, 2024). "Numerous studies have reported associations between FABP4 and the development of metabolic disorders." (PMID 38731797, 2024). "In mouse models and humans, circulating FABP4 levels correlate with the incidence of metabolic disease, and lowering FABP4 levels or activity is associated with improved metabolic health." (PMID 37073893, 2023). "Increased circulating levels of this protein, i.e., FABP4, are known to correlate with the incidence of metabolic diseases, and reduced levels are associated with improved metabolic health." (PMID 36142750, 2022). "That 1-OHP has been found to be associated with serum adipocyte acid binding protein (FABP4), which is used in predicting metabolic diseases and CVDs." (PMID 32726349, 2020). "An elevation of FABP4 concentration is associated with metabolic disorders and cardiovascular events." (PMID 33071982, 2020). "In both preclinical mouse models and humans, levels of circulating FABP4 have been correlated with metabolic disease incidence, and reducing FABP4 levels or activity is associated with improved metabolic health." (PMID 30705117, 2019). "FABP4 is a lipid binding protein that is a therapeutic target for metabolic disorders, and genetic deficiencies of FABP4 have been shown to improve glucose homeostasis." (PMID 28986580, 2017). "Fabp4 encodes fatty acid-binding protein 4, is involved in the regulation of glucose and lipid metabolism in relation to inflammatory and metabolic diseases." (PMID 26712739, 2015). "Further extensive investigations including large-scale, longitudinal clinical trials are paramount to justify the diagnostic and therapeutic potential of FABP4 in maternal–fetal metabolic diseases alongside rigorous safety assessments of its therapeutic application." (PMID 37628833, 2023). "FABP4 is an adipokine recently shown to be linked with cardiovascular and metabolic diseases." (PMID 32075656, 2020). "For instance, pharmacological inhibition of FABP4 is already being investigated for metabolic disorders, while interventions enhancing adiponectin signaling, through PPAR-γ agonists or lifestyle modifications, are known to yield metabolic improvements." (PMID 41187309, 2025). "FABP4 is an important potential target for regulating inflammation and apoptosis in various metabolic diseases and inflammatory processes." (PMID 40072101, 2025). "These future studies are essential to fully establish the clinical utility of FABP4, paving the way for its potential applications in the realm of metabolic disorders." (PMID 38731797, 2024). "Although cellular trafficking of FABP in modulating various metabolic diseases have been proposed, limited data are available on the direct roles of FABP4 in adipose tissue inflammation in human." (PMID 37794302, 2024). "Given the well-known features of FABP4 in metabolic disorders and inflammation, blocking or neutralizing FABP4 by either chemical inhibitors or monoclonal antibodies has emerged as a novel therapeutical strategy." (PMID 37628833, 2023).